LINC00477 (long independently transcribed non-coding RNA 477)
Synonyms: C12orf67; FLJ32894; FAM191B
Gene: Long non-coding RNA gene on chromosome 12 (24,566,964 to 24,584,333, reverse strand). Ensembl gene ENSG00000197503.
Subcellular location: Membrane
Diseases named in the same sentence as LINC00477 in open-access papers:
LINC00477 is named in the same sentence as 1 disease in open-access papers, as found by Europe PMC text mining. Sharing a sentence is not in itself a finding about the gene and the disease.
LINC00477 shares sentences with these, for which no sentence is quoted: gastric cancer (1 paper).